TOMM22-DT (TOMM22 divergent transcript)
Synonyms: lnc408
Gene: Long non-coding RNA gene on chromosome 22 (38,667,585 to 38,681,871, reverse strand). Ensembl gene ENSG00000228274.
Diseases named in the same sentence as TOMM22-DT in open-access papers:
TOMM22-DT is named in the same sentence as 3 diseases in open-access papers, as found by Europe PMC text mining. Sharing a sentence is not in itself a finding about the gene and the disease.
TOMM22-DT shares sentences with these, for which no sentence is quoted: breast carcinoma (1 paper); cancer (1); tumor (1).